TRIM47 (tripartite motif containing 47)
Description:
E3 ubiquitin-protein ligase that mediates the ubiquitination and proteasomal degradation of CYLD.
Synonyms: GOA; RNF100
Tractability: PROTAC: ubiquitination databases record sites on it; its protein half-life has been measured.
Gene: Protein-coding gene on chromosome 17 (75,874,164 to 75,878,581, reverse strand). Ensembl gene ENSG00000132481.
Subcellular location: Cytoplasm; Nucleus
Subcellular location (Human Protein Atlas): Cytosol
Gene Ontology:
Molecular function: ubiquitin protein ligase activity; ubiquitin-protein transferase activity; zinc ion binding
Biological process: protein ubiquitination; regulation of postsynapse assembly
Cellular component: cytosol; cytoplasm; glutamatergic synapse; nucleus; postsynapse
Genetic constraint (gnomAD): Loss-of-function variants: 46 observed, 43.52 expected, observed/expected ratio (o/e) 1.06, 90% interval 0.83 to 1.35. The upper end of that interval is the gene's LOEUF score, 1.35, which puts it in group 5 of 6, group 1 being the genes least tolerant of losing a copy. Missense variants: 825 observed, 747.96 expected, observed/expected ratio (o/e) 1.1, 90% interval 1.04 to 1.17. Synonymous variants: 392 observed, 333.83 expected, observed/expected ratio (o/e) 1.17, 90% interval 1.08 to 1.28.
Homologues: Orthologues: chimpanzee TRIM47 (99% identical), macaque TRIM47 (97% identical), rabbit TRIM47 (92% identical), dog TRIM47 (91% identical), pig TRIM47 (91% identical), rat Trim47 (90% identical), mouse Trim47 (89% identical), guinea pig TRIM47 (85% identical), tropical clawed frog trim45 (18% identical), zebrafish trim45 (17% identical). Paralogues in human: TRIM65 (23% identical), TRIM25 (19% identical), MID1 (19% identical), TRIM45 (18% identical), MID2 (18% identical), TRIM7 (18% identical), TRIM58 (17% identical), TRIM72 (17% identical), TRIM11 (16% identical), TRIM50 (16% identical), TRIM27 (16% identical), TRIM21 (16% identical), and 68 more.
Diseases named in the same sentence as TRIM47 in open-access papers:
TRIM47 is named in the same sentence as 47 diseases in open-access papers, as found by Europe PMC text mining. Sharing a sentence is not in itself a finding about the gene and the disease. The quoted sentences say what the papers report.
breast carcinoma (10 papers, 2021 to 2025). "By analysis the TCGA published profiles of breast cancer, we found that overexpression of TRIM47 was not only associated with relapse-free survival time (P = 0.0031) but also with distant metastasis-free survival time (P = 0.0035) compared with lower TRIM47 expression in breast cancer patients." (PMID 36906594, 2023). "We demonstrated that overexpression of the TRIM47 protein predicted poor prognosis in ER-positive breast cancer patients, and that overexpression of TRIM47 caused endocrine-therapy-resistant growth in breast cancer cell lines." (PMID 35954308, 2022). "For example, TRIM47 facilitates breast cancer proliferation and endocrine therapy resistance by stabilising PKC‐ε/PKD3." (PMID 40801794, 2025). "Recently, TRIM47, a member of the E3 ubiquitin ligase, has been upregulated in a series of human cancers, such as gastric cancer, breast cancer, and hepatocellular carcinoma." (PMID 40801794, 2025). "In summary, TRIM47 was markedly upregulated in TNBC cells and a positive correlation was evident between TRIM47 expression and metastasis-free survival and the relapse-free survival of breast cancer patients." (PMID 36906594, 2023). "Further analysis we found that the mRNA expression of TRIM47 was significantly overexpression in breast cancer compared to normal tissues." (PMID 36906594, 2023). "As for breast cancer, two independent studies including ours showed tumor promoting effects of TRIM47." (PMID 35954308, 2022). "TRIM47 knockdown inhibited the occurrence and development of breast cancer by suppressing the PI3K/Akt pathway, which was reversed by treatment with the PI3K/Akt activator insulin-like growth factor-1 (IGF-1)." (PMID 36249749, 2022). "Among them, we focused on TRIM47, which was recently shown to be related to endocrine resistance in breast cancer." (PMID 35954308, 2022). "Among these, we focused on TRIM47, which was recently shown to be related to endocrine resistance in breast cancer." (PMID 35954308, 2022). "In breast cancer, TRIM47 knockdown suppressed tumorigenesis and progression through inhibition of ATK pathway." (PMID 33982666, 2021). "TRIM47 showed a high expression level in all breast cancer subtypes." (PMID 40635123, 2025). "Mammalian Trim47 has been traditionally linked to oncogenic processes, such as activating NF-κB signaling through its SPRY domain–mediated binding to protein kinase C-ε (PKC-ε), which drives breast cancer proliferation and endocrine resistance." (PMID 40709172, 2025). "Additionally, PI3K/Akt and NF‐κB pathways were also responsible for TRIM47 functions in breast cancer." (PMID 40801794, 2025). "Similarly, knocking down TRIM47 inhibits the migration and invasion of breast cancer by suppressing PI3K/Akt pathway." (PMID 36249749, 2022). "TRIM47 is a poor prognostic factor in both breast cancer and prostate cancer." (PMID 35954308, 2022). "Therefore, further studies are necessary to determine whether TRIM47 upregulation in breast cancer is attributable to genomic amplification or NF-κB/Stat3-mediated transcriptional upregulation." (PMID 36906594, 2023). "Subsequently, we further narrowed down the eight candidate genes (TRIM47, SPHK1, RGMA, ROPN1B, LARP6, ROPN1, NPM2 and LPL) that are shared in TNBC compared to ER+ and HER2+ breast cancer subtypes in cancer cells." (PMID 40635123, 2025). "However, the correlation between TRIM47 and olaparib resistance in breast cancer remains unclear." (PMID 36906594, 2023). "For example, TRIM47, TRIM27, UBR5, and FBXW2 can regulate breast cancer progression and endocrine therapy sensitivities via the polyubiquitination of PKC‐ε, P21, β‐catenin, and MSX2, respectively." (PMID 35843886, 2022). "In addition, TRIM47 overexpression conferred endocrine resistance via PKC‐ε/PKD3 stabilisation and thereby activating NF‐κB signalling in breast cancer." (PMID 40801794, 2025).
breast carcinoma (continued). "Tripartite motif containing 47 (TRIM47), a RING‐type E3 ubiquitin‐protein ligase, was found to be upregulated and correlated with disease progression in several cancers, including gastric cancer, prostate cancer, breast cancer, and glioma." (PMID 40801794, 2025). "Finally, we examined the correlation of TRIM47 and BRCA1 in collected clinical breast cancer samples." (PMID 36906594, 2023).
colorectal cancer (8 papers, 2019 to 2025). A primary or metastatic malignant neoplasm that affects the colon or rectum. "For instance, TRIM52, TRIM37, and TRIM47 have been linked to ovarian cancer invasion, while other members, such as TRIM37 in hepatocellular carcinoma and TRIM24 in colorectal cancer, are known to facilitate metastasis in other cancer types." (PMID 39937005, 2025). "Up-regulation of TRIM47 in colorectal cancers was associated with SMAD4 degradation, enhancing growth and invasion of colorectal cancer cells." (PMID 32226386, 2020). "For example, TRIM47 overexpression promoted colorectal cancer cells proliferation and metastasis via ubiquitination and degradation of SMAD4." (PMID 31823782, 2019). "Real time PCR showed that TRIM47 expression was remarkably up-regulated in 76 of the 100 (76%) colorectal cancer samples compared with the paired adjacent normal tissues (P < 0.01)." (PMID 30979374, 2019). "First, knockdown of TRIM47 increased the expression of SMAD4 in colorectal cancer cells and the data were verified in gain function assay as well." (PMID 30979374, 2019). "First, we detected the expression of TRIM47 in 8 different colorectal cancer cells and normal colorectal cell FHC by real time PCR and western blotting." (PMID 30979374, 2019). "TRIM47 was knocked down and overexpressed in colorectal cancer cells, and the effects on cell proliferation, migration and growth of xenograft tumors in nude mice were assessed." (PMID 30979374, 2019). "TRIM47 protein expression was higher in colorectal cancer tissues than the adjacent tissues (P < 0.05)." (PMID 30979374, 2019). "Functionally, TRIM47 facilitates the proliferation and metastasis of colorectal cancer cell in vitro and in vivo." (PMID 30979374, 2019). "To further validate the effect of TRIM47 on colorectal cancer cell metastasis, we conducted the CRC metastatic mouse model." (PMID 30979374, 2019). "In cultured colorectal cancer cells and xenograft nude mouse models, downregulation of TRIM47 markedly suppresses colorectal cancer cell proliferation and metastasis." (PMID 30979374, 2019). "Second, MG132 treatment, the inhibitor of proteasome, disrupted TRIM47-induced SMAD4 downregulation in colorectal cancer cells." (PMID 30979374, 2019). "To understand the molecular mechanism by which TRIM47 promotes cell proliferation and invasion of colorectal cancer, we examined the protein expression of SMAD4." (PMID 30979374, 2019). "We used quantitative polymerase chain reaction and western blot to measure levels of TRIM47 mRNA and protein in human colorectal cancer and paired normal tissues." (PMID 30979374, 2019). "The results revealed that TRIM47 expression was an independent predictor of colorectal cancer aggressiveness with significant hazard ratios for predicting clinical outcome." (PMID 30979374, 2019). "The results showed that overexpression of SMAD4 significantly reduced colorectal cancer cell proliferation and invasion induced by TRIM47 in SW480 cells." (PMID 30979374, 2019). "The present study provides experimental evidence that TRIM47 is overexpressed significantly in colorectal cancer." (PMID 30979374, 2019). "In summary, our study has shown the biological and clinical significance of TRIM47 in colorectal cancer." (PMID 30979374, 2019). "Furthermore, we examined the effects of TRIM47 on colorectal cancer cell invasion and metastasis function." (PMID 30979374, 2019). "TRIM47 could be regarded as a biomarker to guide early diagnosis and therapy in colorectal cancer patients, and pharmaceutical intervention to TRIM47 expression may provide a promising strategy to improve the outcome of CRC." (PMID 30979374, 2019). "Next, we explored whether the higher expression of TRIM47 in colorectal cancer was related with poor prognosis." (PMID 30979374, 2019).
colorectal cancer (continued). "Since increased research showed that E3 ubiquitin ligase was correlated with drug resistance, we hypothesized that TRIM47 overexpression might affect the chemotherapeutics response of colorectal cancer cells in vitro and in vivo." (PMID 30979374, 2019). "In addition, TRIM47 protein expression was measured by immunohistochemical staining assay in 180 paraffin-embeddded colorectal cancer and adjacent normal tissues (Cohort 2)." (PMID 30979374, 2019). "As TRIM47 has a RING domain in possession of a critical role in the ubiquitination of colorectal cancer as an E3 ligase along with promoting tumor occurrence and metastasis, the group suggested that TRIM47 might facilitate the infiltration of tumor cells by ubiquitination tumor-related genes." (PMID 40618019, 2025). "However, the underlying molecular mechanisms of TRIM47 in colorectal cancer cell growth and metastasis have never been investigated before." (PMID 30979374, 2019). "Mechanistically, TRIM47 promotes the ubiquitination and degration of SMAD4 by interacting with SMAD4, and further increases the levels of C-C motif chemokine ligand 15 (CCL15) and C-C motif chemokine receptor 1 (CCR1), ultimately causing poor outcome of colorectal cancer." (PMID 30979374, 2019). "TRIM47 has a RING structure and has been shown to play a role of ubiquitination in colorectal cancer as an E3 ligase, thereby promoting tumor occurrence and metastasis." (PMID 33622324, 2021). "Tripartite motif 47 (TRIM47), a member of the TRIM family proteins, plays a key role in many types of cancers including colorectal cancer (CRC)." (PMID 30979374, 2019). "TRIM47, also known as GOA (Gene overexpressed in astrocytoma protein), was upregulated and possessed oncogenic function in multiple types of tumors, such as non-small cell lung carcinoma (NSCLC), colorectal cancer (CRC) and prostate cancer (PC)." (PMID 39567506, 2024). "However, the pathologic and clinical role of TRIM47 has not been revealed in colorectal cancer." (PMID 30979374, 2019).
glioma (8 papers, 2021 to 2025). A benign or malignant brain and spinal cord tumor that arises from glial cells (astrocytes, oligodendrocytes, ependymal cells). "Compared to that in normal tissues, TRIM47 expression was greatly higher in glioma tissues, and its expression level was associated with different grades of glioma." (PMID 33833824, 2021). "Our data indicated that highly expressed TRIM47 displayed an association with the poor prognosis of glioma patients." (PMID 33833824, 2021). "TRIM47 has a role in promoting the development of glioma by ubiquitination and degradation of FOXO1." (PMID 37367937, 2023). "Results demonstrated that TRIM5(AUC = 0.938)/17(AUC = 0.829)/21(AUC = 0.934)/22(AUC = 0.867)/24(AUC = 0.990)/28(AUC = 0.898)/34(AUC = 0.949)/TRIM47(AUC = 0.951) exposed excellent accuracy in gliomas." (PMID 37367937, 2023). "Knockdown experiments in TRIM47-highly expressing glioma cell lines, attenuated the proliferative, invasive, and migratory potential of these cells and decreased the expression of EMT markers, while an abrogation of tumor growth was observed in vivo." (PMID 36139694, 2022). "TRIM47 expression was shown to have a prognostic value in gliomas as a marker for poorer overall survival (OS)." (PMID 36139694, 2022). "While downregulation of TRIM47 lowered the expression levels of β-catenin, c-MYC, and cyclin D1, exogenous activation of Wnt/β-catenin signaling abolished the previous effects of TRIM47 knockdown observed in glioma cells." (PMID 36139694, 2022). "Taken together, all these results demonstrated that high TRIM47 expression predicted poor OS and was a poor prognosis factor in glioma." (PMID 33833824, 2021). "Public database analysis was applied to analyze TRIM47 expression, and quantitative real-time PCR (qRT-PCR) was applied to detect the expression of TRIM47 in 9 paired tissues of glioma." (PMID 33833824, 2021). "Nevertheless, it is not well understood regarding the expression, prognostic value, and function of TRIM47 in glioma." (PMID 33833824, 2021). "The high expression of TRIM47 had a significant correlation with the shorter OS of patients with glioma." (PMID 33833824, 2021). "The TRIM47 level in glioma specimens was measured, and the relationship between TRIM47 and glioma was then studied utilizing several biological assays." (PMID 33833824, 2021). "After knocking down TRIM47, we found that glioma cell proliferation, migration, and invasion were inhibited." (PMID 33833824, 2021). "Based on what was mentioned previously, TRIM47 is a prospective biomarker for glioma and has the potentiality to become a newly generated target for glioma treatment." (PMID 33833824, 2021). "All data imply that TRIM47 is a probable biomarker for glioma and has the potentiality to become a newly generated target for glioma treatment." (PMID 33833824, 2021). "In vitro experiments were performed to validate TRIM47-mediated effects on glioma cell proliferation, migration, and invasion." (PMID 33833824, 2021). "The results showed that TRIM47 was significantly overexpressed in glioma, and the expression level of TRIM47 was positively correlated with the WHO grades of glioma." (PMID 33833824, 2021). "Heightened TRIM47 expression levels were accompanied by the increase of glioma WHO grade in the CGGA database." (PMID 33833824, 2021). "All the data implied that TRIM47 was a prospective oncogene in glioma and its expression was related to the grade of neoplasm." (PMID 33833824, 2021). "In future studies, we will collect more clinical samples and clinical parameters of glioma patients, including age, gender, and survival time, to further explore the function of TRIM47 in glioma." (PMID 33833824, 2021).
glioma (continued). "In addition, other studies have shown that the expression of TRIM47 is closely related to human glioma and prostate cancer." (PMID 40618019, 2025). "TRIM47 promotes the proliferation, migration, and invasion of glioma cells, while the role of TRIM56 in gliomas remains unclear." (PMID 36870986, 2023). "TRIM47 expression was found to be elevated in glioma specimens compared to normal brain tissues." (PMID 36139694, 2022). "Thus, it is necessary to make further investigation towards the relationship between TRIM47 and glioma." (PMID 33833824, 2021). "TRIM47 expressions were determined in glioma tissues and cell lines." (PMID 33833824, 2021). "Next, we further validated the impacts of TRIM47 on the migrated and invasive glioma cells." (PMID 33833824, 2021). "In short, TRIM47 can promote the biological activities of glioma cells and tumors." (PMID 33833824, 2021). "Up to now, it is yet unclear about the impacts of TRIM47 on glioma proliferation and metastasis." (PMID 33833824, 2021). "Our data suggested that the level of TRIM47 could be regarded as a promising indicator for glioma prognosis." (PMID 33833824, 2021). "The prognostic value of TRIM47 in glioma patients was evaluated in this part." (PMID 33833824, 2021). "Furthermore, the CGGA database was also applied to explore the links between TRIM47 expression level and the OS of glioma patients." (PMID 33833824, 2021). "In our study, we attempted to systematically validate TRIM47 function in glioma." (PMID 33833824, 2021). "We identified the DEGs in glioma patients with high and low expression of TRIM47." (PMID 33833824, 2021). "Our findings collectively suggested that TRIM47 could be regarded as a modulator of glioma cell development." (PMID 33833824, 2021). "Ablating TRIM47 obviously impeded glioma cell invasion and migration." (PMID 33833824, 2021). "All data collectively indicate that TRIM47 is a prospective biomarker of glioma." (PMID 33833824, 2021). "A recent study has demonstrated that knockdown of TRIM47 suppressed cell proliferation and metastasis of glioma cells via negatively regulating Wnt signalling; therefore, we explored whether the Wnt/β‐catenin pathway was also accountable for TRIM47 function in osteosarcoma." (PMID 40801794, 2025). "All these indicated that TRIM47 might be an important indicator for gliomas and their malignancy." (PMID 33833824, 2021). "In addition, the regulatory mechanism involved in TRIM47 in gliomas will be further studied." (PMID 33833824, 2021). "TRIM47 could modulate glioma cell proliferation, invasion, and migration." (PMID 33833824, 2021). "Finally, we performed the CCK-8 assay and Transwell assay to detect TRIM47 function in glioma." (PMID 33833824, 2021). "Highly expressed TRIM47 could promote glioma cell proliferation, migration, and invasion." (PMID 33833824, 2021). "Thus, we further determined the potential of TRIM47 predicting the prognosis of glioma." (PMID 33833824, 2021). "Another TRIM that influences C-MYC is TRIM47 (class IV), whose knockdown instead reduces levels of C-MYC as well as β-Catenin and Cyclin-D1 in glioma cells." (PMID 38115822, 2023). "TRIM24, TRIM47, TRIM44, TRIM31, TRIM14, TRIM21, and TRIM28 have exhibited significant prognostic value regarding OS and/or PFS of glioma patients." (PMID 36139694, 2022). "Of interest, our data suggested that the level of TRIM47 was largely raised in glioblastoma multiforme (GBM) and lower-grade glioma (LGG) tissues after GEPIA database analysis." (PMID 33833824, 2021). "These outcomes revealed that TRIM47 had a high expression in the samples and cell lines of glioma, not in normal tissues." (PMID 33833824, 2021).